PRAMEF33 (PRAME family member 33)
Synonyms: PRAMEF33P
Gene: Protein-coding gene on chromosome 1 (13,303,539 to 13,308,907, forward strand). Ensembl gene ENSG00000237700.
Gene Ontology:
Molecular function: ubiquitin-like ligase-substrate adaptor activity
Biological process: proteasome-mediated ubiquitin-dependent protein catabolic process; negative regulation of apoptotic process; negative regulation of cell differentiation; negative regulation of DNA-templated transcription; positive regulation of cell population proliferation
Cellular component: Cul2-RING ubiquitin ligase complex; cytoplasm
Genetic constraint (gnomAD): Loss-of-function variants: 4 observed, 5.79 expected, observed/expected ratio (o/e) 0.69, 90% interval 0.34 to 1.53. That is too few expected variants to judge how well the gene tolerates losing a copy. Missense variants: 43 observed, 96.67 expected, observed/expected ratio (o/e) 0.44, 90% interval 0.35 to 0.57. Synonymous variants: 17 observed, 34.12 expected, observed/expected ratio (o/e) 0.5, 90% interval 0.34 to 0.75.
Homologues: Orthologues: mouse Pramel12 (44% identical), rat Pramef8 (44% identical), rat Pramef5 (40% identical), mouse Pramel20 (39% identical), mouse Pramel43 (39% identical), rat LOC120103107 (39% identical), mouse Gm13040 (39% identical), mouse Gm13043 (39% identical), mouse Gm13057 (39% identical), mouse Pramel13 (39% identical), mouse Pramel16 (39% identical), mouse Pramel21 (39% identical), and 78 more. Paralogues in human: PRAMEF10 (99% identical), PRAMEF17 (88% identical), PRAMEF18 (62% identical), PRAMEF19 (62% identical), PRAMEF1 (60% identical), PRAMEF14 (59% identical), PRAMEF13 (59% identical), PRAMEF2 (58% identical), PRAMEF12 (53% identical), PRAMEF8 (53% identical), PRAMEF7 (52% identical), PRAMEF20 (50% identical), and 12 more.